EXTL2 (exostosin like glycosyltransferase 2)
Description:
Glycosyltransferase required for the biosynthesis of heparan-sulfate and responsible for the alternating addition of beta-1-4-linked glucuronic acid (GlcA) and alpha-1-4-linked N-acetylglucosamine (GlcNAc) units to nascent heparan sulfate chains.
Synonyms: EXTR2
Tractability: Antibody: UniProt places it where antibodies can reach, with medium confidence; UniProt predicts a signal peptide or a membrane-spanning region; its Gene Ontology location is reachable by antibodies, with medium confidence. PROTAC: its protein half-life has been measured.
Gene: Protein-coding gene on chromosome 1 (100,872,372 to 100,896,000, reverse strand). Ensembl gene ENSG00000162694.
Subcellular location: Endoplasmic reticulum membrane; Secreted (Processed exostosin-like 2)
Subcellular location (Human Protein Atlas): Nucleoplasm; Cytosol
Pathways (Reactome):
Cellular responses to stimuli: XBP1(S) activates chaperone genes
Metabolism: HS-GAG biosynthesis
Gene Ontology:
Molecular function: alpha-1,4-N-acetylgalactosaminyltransferase activity; glucuronyl-galactosyl-proteoglycan 4-alpha-N-acetylglucosaminyltransferase activity; protein binding; acetylglucosaminyltransferase activity; glucuronylgalactosylproteoglycan 4-beta-N-acetylgalactosaminyltransferase activity; glycosaminoglycan binding; glycosyltransferase activity; manganese ion binding
Biological process: N-acetylglucosamine metabolic process; UDP-N-acetylgalactosamine metabolic process; heparan sulfate proteoglycan biosynthetic process
Cellular component: endoplasmic reticulum; endoplasmic reticulum membrane; Golgi membrane; extracellular region; membrane
Genetic constraint (gnomAD): Loss-of-function variants: 18 observed, 25.33 expected, observed/expected ratio (o/e) 0.71, 90% interval 0.49 to 1.05. The upper end of that interval is the gene's LOEUF score, 1.05, which puts it in group 4 of 6, group 1 being the genes least tolerant of losing a copy. Missense variants: 322 observed, 378.58 expected, observed/expected ratio (o/e) 0.85, 90% interval 0.78 to 0.93. Synonymous variants: 117 observed, 129.76 expected, observed/expected ratio (o/e) 0.9, 90% interval 0.77 to 1.05.
Homologues: Orthologues: chimpanzee EXTL2 (99% identical), macaque EXTL2 (98% identical), rabbit EXTL2 (90% identical), dog EXTL2 (90% identical), guinea pig EXTL2 (89% identical), pig EXTL2 (88% identical), mouse Extl2 (87% identical), rat Extl2 (85% identical), tropical clawed frog extl2 (66% identical), zebrafish extl2 (60% identical). Paralogues in human: EXT2 (30% identical), EXTL3 (30% identical), EXT1 (29% identical), EXTL1 (25% identical).
Diseases named in the same sentence as EXTL2 in open-access papers:
EXTL2 is named in the same sentence as 14 diseases in open-access papers, as found by Europe PMC text mining. Sharing a sentence is not in itself a finding about the gene and the disease. The quoted sentences say what the papers report.
breast carcinoma (1 paper, 2020). "In the light cyan module, Extl2 (Exostosin-like 2) codes for a glycosyltransferase from the exostosin family that modifies the heparin sulfate structure and is involved with breast cancer cell adhesion and invasion." (PMID 32831131, 2020).
exostoses (1 paper, 2020). "Considering that dominant mutations in EXT1 and EXT2 genes cause hereditary multiple exostoses and the EXTL1 gene is expressed at very low levels in brain cells, EXTL2 and EXTL3 represent the most promising candidates in this pathway for SRT." (PMID 32121121, 2020).
gastric cancer (1 paper, 2022). A primary or metastatic malignant neoplasm involving the stomach. "For this purpose, we have established glycoengineered gastric cancer cell models by knocking out either EXTL2 or EXTL3 from MKN74 cells and evaluated the impact of both glycosyltransferase KOs over GAG biosynthesis." (PMID 36181793, 2022). "In conclusion, we showed that the abrogation of the tumor suppressor gene EXTL2 in gastric cancer cells contributes to aggressive cellular features, such as increased motility and invasion." (PMID 36181793, 2022). "We showed that EXTL3 is key for initiating the synthesis of HS chains in detriment of CS biosynthesis, intervening in the fine-tuned balance of the HS/CS ratio in cells, while EXTL2 functions as a negative regulator of HS biosynthesis, with impact over the glycoproteome of gastric cancer cells." (PMID 36181793, 2022). "Interestingly, our results showed that abrogation of EXTL2 and subsequent cellular HS increase resulted in decreased EphA 4 activation in gastric cancer cells." (PMID 36181793, 2022). "In the present study, we disclosed the regulatory roles of EXTL2 and EXTL3 in GAG and HSPG biosynthetic pathways, in the context of gastric cancer, and evaluated the impact of the resulting altered GAGosylation in cancer cells’ motility and signaling features." (PMID 36181793, 2022). "To uncover the impact of specific GAGosylation profiles from EXTL2 KO and EXTL3 KO gastric cancer cells in the activation of RTKs, we screened the phosphorylation state of multiple RTKs using a phospho array." (PMID 36181793, 2022). "In this study, we established glycoengineered gastric cancer cell models lacking either exostosin-like glycosyltransferase 2 (EXTL2) or EXTL3 and revealed their regulatory roles in both HS and chondroitin sulfate (CS) biosynthesis and structural features." (PMID 36181793, 2022). "In this work, we have evaluated the roles of EXTL2 and EXTL3 in HS biosynthesis in gastric cancer." (PMID 36181793, 2022). "Similarly, we hypothesize that in our EXTL2 KO cell models, lack of EXTL2 expression in MKN74 gastric cancer cells could lead to the accumulation of phosphorylated tetrasaccharides that are not capped with GlcNAc residues and are thus available to undergo this particular CS biosynthesis pathway." (PMID 36181793, 2022).
meningioma (1 paper, 2023). A generally slow growing tumor attached to the dura mater. "In the study, miR-3605-5p, miR-664b-5p, PNRC2, BTBD8, SLFN13, DGKD, NSD2, EXTL2, and BVES were closely corrected with the malignant progression of meningioma." (PMID 37024523, 2023).
multiple sclerosis (1 paper, 2022). A progressive autoimmune disorder affecting the central nervous system resulting in demyelination. "Interestingly, genetic variation in both VCAM1 and EXTL2 is associated with blood cell counts and multiple sclerosis, according to the GWAS catalog." (PMID 35754128, 2022).
myeloma (1 paper, 2013). "Enzymes relevant for the initiation of GAG formation and heparan sulfate chain elongation, beta-1,3-glucuronyltransferase 3 (B3GAT3), multiple exostosin-like 2 (EXTL2) and EXT2 heparan sulfate copolymerase (EXT2), display enhanced expression in myeloma cells." (PMID 24386263, 2013).
pancreatic cancer (1 paper, 2025). "Among the upregulated proteins in the exosomes of patients with pancreatic cancer, exostosin-like glycosyltransferase 2 (EXTL2), α-2-macroglobulin like 1 (A2ML1), and Parkinson's disease protein 7 (PARK7) were the most significantly overexpressed." (PMID 40331617, 2025).
Sanfilippo syndrome (1 paper, 2015). "The search for novel shRNAs, stable and highly inhibitory for EXTL2 (the best target, according to our results and those of other authors) is a necessary next step on the way to achieving a successful SRT for Sanfilippo syndrome." (PMID 26347037, 2015).
triple-negative breast carcinoma (1 paper, 2018). An invasive breast carcinoma which is negative for expression of estrogen receptor (ER), progesterone receptor (PR), and human epidermal growth factor receptor 2 (HER2). "The two triple-negative breast carcinoma cell lines exhibited a similar pattern of EXT gene expression with significantly increased expression of EXTL2 and reduced expression of EXTL3." (PMID 30054430, 2018).
tumor (6 papers, 2011 to 2024). "Further analysis of related functions revealed the possibility that cuproptosis-related glycosyltransferase Exostosin-like 2 (EXTL2) participated in tumor immunity." (PMID 36496988, 2022). "In the subnetwork related to tumor progression, the hubs from the blue module are the most connected, such as the genes Cmas, Kmt2a, Golt1b, Cdc34, Manf, Sco1, and Thoc3, followed by hubs from the light cyan (Extl2, Commd3, Wdr41, Keap1, Osbpl9) and pink modules." (PMID 32831131, 2020). "All four genes (EXTL2, EXTL3, EXT1, and EXT2) involved in elongation of the backbone of HS chains are significantly >2-fold upregulated in tumor compared to the adjacent benign tissues." (PMID 33585200, 2020). "EXTL2, a member of the tumor suppressor EXT gene family, shaped tumor cell motility and invasion." (PMID 38331878, 2024). "A number of genes demonstrated reduced copy number and expression in KRAS mutant tumours, including putative tumour suppressor genes (FOXO3, EXTL2, PPP2R1B), negative regulators of the receptor tyrosine kinase oncogenic pathways (PTPRK, DGKZ, NCAM1), and negative regulators of Ras (EPHB2)." (PMID 21385341, 2011).
cancer (4 papers, 2018 to 2026). A tumor composed of atypical neoplastic, often pleomorphic cells that invade other tissues. "In order to assess if EXTL2 KO would also impact cancer cell invasion, we evaluated cells’ ability to break down and penetrate matrigel-coated membranes, which is a basement membrane–like matrix, enriched in ECM proteins." (PMID 36181793, 2022). "To determine the functional impact of altered GAGosylation in cancer cell motility, we performed wound healing assays and evaluated the migration rates of EXTL2 KO and EXTL3 KO cells on fibronectin and collagen IV coated surfaces." (PMID 36181793, 2022). "Previous studies have reported that CA9, EXTL2, PGAM1, and TYMS were dysregulated across multiple human cancers and intricately associated with tumorigenesis by functioning as key enzymes underlying metabolism." (PMID 33425725, 2020). "The expression of EXT2 and EXTL3 was reduced in all cancer cell lines whereas EXTL2 was down-regulated in MCF7 cells but highly up-regulated in MDA-MB-231, and HCC38." (PMID 30054430, 2018). "Conversely, EXTL1, EXTL2, and EXTL3 showed inconsistent and context-specific expression patterns across cancers." (PMID 41438585, 2026). "Currently, there is very limited knowledge regarding the expression and impact of EXTL2 and EXTL3 in the context of cancer pathologies." (PMID 36181793, 2022). "Our findings uncover the biosynthetic roles of EXTL2 and EXTL3 in the regulation of cancer cell GAGosylation and proteoglycans expression and unravel the functional consequences of aberrant HS/CS balance in cellular malignant features." (PMID 36181793, 2022). "To characterize HS and CS glycan structures from EXTL2 KO and EXTL3 KO glycoengineered cancer cell lines, we isolated and purified cellular GAGs and performed HS and CS disaccharide analyses using reversed-phase ion pair HPLC (RPIP-HPLC)." (PMID 36181793, 2022).
neurological disorders (1 paper, 2020). "In addition, it will be interesting to examine LAMP2- and HS-related phenotypes in iAs, due to the important role of astrocytes in neurological disorders and the potential of SRT targeting EXTL2 and EXTL3 in iAs." (PMID 32121121, 2020).
EXTL2 also shares sentences with these, for which no sentence is quoted: asthma (1 paper); Sanfilippo C syndrome (1).